GPC3 (glypican 3)
Diseases named in the same sentence as GPC3 in open-access papers (continued):
Sharing a sentence is not in itself a finding about the gene and the disease.
pancreatic adenocarcinoma (1 paper, 2024). "GPC3 expression was observed in 1/72 (1.4%) pancreatic adenocarcinomas and in 0/20 (0%) pancreatic NETs." (PMID 39598037, 2024). "While there are no studies other than Yao’s study and our study that attempted to look at GPC3 expression as a potential prognostic and predictive marker for pancreatic adenocarcinoma, there are some studies where a rate of expression of GPC3 in pancreatic adenocarcinoma can be found." (PMID 39598037, 2024). "However, if GPC3 was indeed expressed in a significant proportion of pancreatic adenocarcinomas, it would have very significant implications beyond prognostication." (PMID 39598037, 2024).
polydactyly (1 paper, 2024). A disease characterized by the presence of polydactyly, including syndromic and non-syndromic forms. "In mice, mutation of glypican-3 leads to defects such as Polydactyly." (PMID 39056781, 2024).
polyp (1 paper, 2024). A usually exophytic mass attached to the underlying tissue by a broad base or a thin stalk. "Significant dysregulation of the expression of critical genes, including DKK1, GPC3, BMP7, FGF17, and WNT10B, was observed in the PPI network; this dysregulation could potentially be associated with the proliferation of polyp tissues." (PMID 38473810, 2024). "DKK1 and DKKL1 showed a significant upregulation in polyp specimens, while WNT10B, GREM1, RSPO3, SFRP5, and GPC3 showed a downward trend." (PMID 38473810, 2024).
Portal vein thrombosis (1 paper, 2021). Thrombosis of the portal vein and/or its tributaries, which include the splenic vein and the superior and inferior mesenteric veins. "Glypican-3 (GPC3) showed a significant positive correlation with alpha-fetoprotein expression, while elevated alpha-fetoprotein level has reported to be associated with portal vein thrombosis." (PMID 33996895, 2021).
rectum adenocarcinoma (1 paper, 2025). An adenocarcinoma arising from the rectum. "CYP7B1 was a negative prognostic factor for ACC, while GPC3 correlated with unfavorable prognosis of UVM and rectum adenocarcinoma (READ)." (PMID 40433364, 2025).
renal dysplasia (1 paper, 2015). Renal dysplasia is a form of renal malformation in which the kidney(s) are present but their development is abnormal and incomplete. "Meanwhile, Gpc3 knockout mice display increased body mass, renal dysplasia, and perinatal mortality." (PMID 26377847, 2015).
spindle cell sarcoma (1 paper, 2026). A malignant mesenchymal neoplasm composed of spindle-shaped cells. "Histopathological analysis of the metastatic lesion revealed spindle cell sarcoma with decreased GPC-3/Hepa expression and elevated CD34/Ki-67 expression." (PMID 41908529, 2026).
squamous non-small cell lung cancer (1 paper, 2017). "However, our study revealed that GPC3 is not expressed in either gastric glands or kidney tissue; we also demonstrated its expression in approximately 70% of HCC and 63% of squamous non-small cell lung cancer." (PMID 28881778, 2017).
Stroke (1 paper, 2012). Sudden impairment of blood flow to a part of the brain due to occlusion or rupture of an artery to the brain. "However, one third of the genes were increased with suboptimal timing in aged rats, either on day 3 post-stroke (Adam17, Gpc3, Mmp14, Nid2, Tagln, Wnt5b) or on day 14 after stroke (Col4a2, Col8a1, Cthrc1, Cxcl1, Gpc3, Tgfbr2)." (PMID 23251410, 2012).
Tetralogy of Fallot (1 paper, 2023). A congenital cardiac malformation comprising pulmonary stenosis, overriding aorta, ventricular septum defect, and right ventricular hypertrophy. "Pathogenic mutations in the NR2F2 and GPC3 will lead to many cardiac defects, such as VSD, Tetralogy of Fallot and double outlet right ventricle." (PMID 36874970, 2023).
trophoblastic tumor (1 paper, 2010). "GPC3 may be useful as an additional immunohistochemical marker to distinguish PSTT from non-trophoblastic tumors common to the uterus." (PMID 20868507, 2010). "GPC3 may be a useful adjunct immunohistochemical marker in differentiating PSTT from non-trophoblastic tumors." (PMID 20868507, 2010).
Turner syndrome (1 paper, 2004). Turner syndrome is a chromosomal disorder associated with the complete or partial absence of an X chromosome. "In order to test the hypothesis that GPC3 promoter methylation in females is linked to the inactive X chromosome, the PCR-based methylation assay was performed on peripheral blood DNA samples from two Turner syndrome patients with karyotype (45, X), having no inactive X chromosome." (PMID 15083193, 2004).
tumor (680 papers, 2002 to 2026). "Combining clinical data and the immunocompetent orthotopic HCC model, we demonstrate that TREM2+ tumor-associated macrophages (TAMs) are critical mediators of GPC3-CAR-T resistance." (PMID 41564864, 2026). "Kaplan–Meier and multivariate Cox analyses demonstrated that serum GPC-3 levels > 150 pg/mL were independently associated with reduced OS, even after adjusting for tumor stage and therapy." (PMID 41511652, 2026). "In this single-center cohort study of patients with unresectable HCC treated with AB combination therapy, we demonstrated that tumor GPC3 expression was significantly associated with worse OS and lower ORR, but not with PFS." (PMID 41463223, 2025). "Additional histologic markers such as Glypican-3, Arginase-1, and HepPar-1 help refine diagnostic accuracy, particularly in poorly differentiated tumours." (PMID 41583252, 2025). "This suggests that GPC3 expression is associated with a reduced likelihood of achieving radiologic tumor response to AB therapy." (PMID 41463223, 2025). "Regulating the tumor microenvironment: GPC3 is up-regulated in the cancer-associated fibroblasts (CAFs) subgroups within the advanced GC and is correlated with poor prognosis in GC patients." (PMID 40422229, 2025). "We analyzed tumor biopsy samples to determine GPC3 expression patterns and investigated their association with clinical outcomes." (PMID 41463223, 2025). "This prompted us to develop novel radiolabeled analogs of TJ12P2 for the imaging of tumor-associated GPC3." (PMID 41304901, 2025). "Overexpression of glypican-3 (GPC3) has also emerged as a hallmark of aggressive tumor phenotypes, correlating with shortened overall and disease-free survival, and representing a promising therapeutic target in HCC." (PMID 40601653, 2025). "In solid tumors, the most commonly targeted tumor-associated antigens (TAAs) include CEA, HER2, GPC3, and EpCAM, whereas tumor-specific antigens (TSAs) are relatively rare, which significantly limits the application of CAR-T cell therapy in solid tumors." (PMID 39350256, 2024). "Glypican-3 (GPC3), a protein intimately associated with tumorigenesis and tumor progression, has been identified to play a pivotal role." (PMID 39867891, 2024). "Previous studies have shown that GPC3 is actively involved in the regulation of HCC tumor growth, and positive expression of GPC3 is associated with poor clinical prognosis in HCC patients." (PMID 38023195, 2023). "Serum levels of GPC3 can be detected using enzyme-linked immunosorbent assay (ELISA), and immunohistochemistry (IHC) can confirm its expression in tumor tissues." (PMID 38173713, 2023). "A high level of GPC-3 detected in blood serum is associated with poor prognosis and later stage tumor detection, vascular invasion, and metastases, also a rapid increase of GPC-3 expression is associated with the transition of precancerous lesions to HCC." (PMID 35326644, 2022). "Recent studies have shown that the function of GPC3 can also be linked to the tumor microenvironment." (PMID 35050429, 2022). "Diagnostic power in predicting GPC3-positive HCC was highest for the combination of tomoelastography-quantified tumor stiffness and serum marker AFP." (PMID 36518314, 2022). "We investigated MCC GPC3 expression by immunohistochemistry (IHC) and its association with tumor characteristics, MCPyV status, and patient outcome." (PMID 35937502, 2022). "Aberrant GPC3 expression is implicated in tumorigenesis, and GPC3+ cancers are characterized by a highly immunosuppressive landscape which induces exhaustion in tumor-resident T cells." (PMID 35937502, 2022).
tumor (continued). "Intriguingly, ectopic MYC in MET tumours increases expression of the Mki67 proliferation marker, and switches them into loss of Afp, Spp1, Gpc3, Epcam accompanied by an increase in Hgma1, Vim, and Hep-Par1 levels." (PMID 36433941, 2022). "The split GPC3-CAR-T suppressed tumor growth also reduced the risk of severe cytokine release syndrome in vitro and xenograft mice model." (PMID 34372912, 2021). "Lower intensity PET signal was observed in the center of larger tumors, suggesting diminished conjugate delivery secondary to poor perfusion and/or tumor cell necrosis and loss of GPC3 surface expression." (PMID 33580090, 2021). "High GPC3 expression was also extensively associated with worse tumor differentiation, later tumor stage, presence of vascular invasion, and hepatitis B virus (HBV) infection." (PMID 35141153, 2021). "Immunohistochemical staining of the tumor nodules revealed intense expression of glypican-3 (Gpc3), a diagnostic marker for HCC." (PMID 34771521, 2021). "In our study, we found the similar results that high GPC-3 expression levels were associated with tumor size and poor OS and DFS." (PMID 34715880, 2021). "GPC3 is also elevated in tumor tissue by IHC, which is a clinical hallmark of HB tumor and more pronounced in PDX." (PMID 34497364, 2021). "Recent studies demonstrated that greater GPC-3 expression in tumor cells was associated with a worse prognosis for HCC." (PMID 33450845, 2021). "In BsAb therapy, while one antibody activates the effector T cell receptors such as CD3 and CD28, the other antibody causes a tumor-associated antigen, such as AFP, GPC3, and EpCAM, to initiate tumor cytotoxicity." (PMID 34696292, 2021). "HCC expresses multiple tumor-associated antigens with identified immunogenicity (GPC3, AFP, SSX-2, NY-ESO-1, EpCAM, and midkine)." (PMID 34440678, 2021). "Another example of a gene with altered expression is the GPC3 gene encoding glypican-3, which is overexpressed in HepG2 cells and tumor cells in HCC." (PMID 34884942, 2021). "According to the aggregate indicators of diagnostic efficiency, heparin-binding growth factor, glypican-3, and osteopontin are the most promising tumor markers of those studied." (PMID 34513063, 2021). "Univariate analyses revealed that Arg-1 and GPC-3 levels, tumor size, tumor number, lymph node metastasis, vascular invasion, and tumor stage were associated with tumor growth." (PMID 34715880, 2021). "One of the potential TAA tumor-associated antigens is Glypican-3 (GPC3), belonging to the heparan sulfate proteoglycan family, is a polyglycoprotein anchored to the cell membrane." (PMID 34261411, 2021). "In another metanalysis, similar observations were reported, associating Glypican-3 with aggressive histological tumor features (dedifferentiation and vascular invasion)." (PMID 32492896, 2020). "Knockdown of GPC3 expression was associated with tumor growth suppression, which was significantly reversed forcing the expression of HIF-1α." (PMID 32585931, 2020). "The high expression of GPC3 was significantly associated with malignant events such as poor tumor differentiation, advanced stage of tumor, vascular invasion, and HBV infection." (PMID 32127929, 2020). "GPC3 is involved in the regulation of cell division and growth and its expression in tumor cells was previously associated with poor prognosis for HCC." (PMID 33117354, 2020). "Glypican 3 (GPC-3) is a heparan sulfate proteoglycan that plays an important role in cell proliferation and differentiation, and is found to be highly associated with tumor development." (PMID 33297335, 2020). "Tumor-associated macrophages express glypican-3, and therefore, anti-glypican-3 antibodies are intended for therapeutic usage." (PMID 31491903, 2019). "In the subset of patients with glypican-3 positive tumors, adjuvant glypican-3 vaccination was associated with a reduction in tumor recurrences (24% vs. 48%, p = 0.047)." (PMID 31366113, 2019).
tumor (continued). "Because of this differential expression and cell surface location, GPC3 is a promising tumor marker for diagnostic and therapeutic purposes in HCC." (PMID 31636665, 2019). "Both ELISA and IHC studies demonstrated that glypican-3 (GPC3) would be a promising diagnostic tumor marker for N-HCC." (PMID 31635078, 2019). "Taken together, disruption of PD-1 enhanced the inhibition of tumor-relate genes expression in xenografts caused by the GPC3-CAR T cells." (PMID 30327605, 2018). "Combing CK19/GPC3 sub-typing, histological grading and tumor number into MC, a model to stratify the risk of recurrence of HCC patients after RR was devised." (PMID 28968990, 2017). "GPC3 is one of the well-studied HCC-associated tumor antigens, and its specific CTL has been identified both in patients with HCC and in mice." (PMID 28445973, 2017). "Loss-of-function mutations in GPC3 cause Simpson-Golabi-Behmel syndrome, a disease that is characterized by prenatal and postnatal overgrowth and an increased risk of embryonal tumor development." (PMID 29113314, 2017). "To understand how the loss-of-GPC3 increases the capacity of tumor cells to invade, we analyzed the activation status of MAPK signaling, a pathway involved in the regulation of invasion and metastasis." (PMID 27259271, 2016). "Molecular studies revealed the activation of MAPK kinases and FoxM1 after loss of GPC3 in tumor cells." (PMID 27259271, 2016). "The molecular and immunohistochemical analysis performed in our human CRC set revealed very similar results, indicating the significant association of GPC1 over-expression and GPC3 under-expression in tumor lesions with respect to the normal colon mucosa." (PMID 26517809, 2015). "GPC3 overexpression was significantly associated with high tumor grade (OR: 3.30, 95% CI: 2.04–5.33), late TNM stage (OR: 2.26, 95% CI: 1.00–5.12), and the presence of vascular invasion (OR: 2.43, 95% CI: 1.23–4.82)." (PMID 24548704, 2014). "Taking into account the association between tumor invasion and GPC3 expression profile, in the present study, we also carried out pooled analyses of the association between GPC3 expression and tumor pathological features." (PMID 24548704, 2014). "The effects of loss of GPC3 on tumor development are compatible with its function as a tumor suppressor, since this molecule is an inhibitor of cell proliferation and can induce apoptosis." (PMID 24570896, 2014). "We found that GPC3 expression in the tumor increased F4/80+CD86+ macrophage (M1) proportion and caused GPC3-specific CD8+ T cell immune responses, and prolonged mouse survival." (PMID 24992906, 2014). "Next, we investigated the capacity of this culture method to induce expansion of CTLs specific for peptides derived from the weakly immunogenic tumor-associated self-antigen GPC3." (PMID 25189159, 2014). "The aim of this study was to investigate the expression of GPC3 in PSTT by immunohistochemistry to evaluate its potential as an additional diagnostic marker for this tumor." (PMID 20868507, 2010). "This discrepancy presence may contribute to the differential regulation of GPC3 variants during tumor growth." (PMID 39841705, 2025). "In addition to hepatic differentiation markers, the expression of tumor-associated markers (GPC3, SPP1, SPINK1, and KPNA2) was examined across all cell models." (PMID 40862732, 2025). "Given that GPC3 is also implicated in tumor invasiveness and stem cell-like characteristics, GPC3+ CTCs present in the portal vein may signify a population of highly malignant cells with a high potential for recurrence." (PMID 40924249, 2025). "We evaluated whether tumor GPC3 expression is associated with clinical outcomes in patients with advanced HCC treated with atezolizumab–bevacizumab (AB)." (PMID 41463223, 2025). "However, AFP levels were significantly higher in the GPC3-positive group, consistent with the association between GPC3 expression and elevated tumor marker burden." (PMID 41463223, 2025).